ENSG00000276730
Gene: Miscellaneous RNA gene on chromosome 9 (36,072,686 to 36,072,762, forward strand). Ensembl gene ENSG00000276730.
Gene Ontology:
Molecular function: catalytic activity
Homologues: Orthologues: mouse Gm56265 (91% identical).